ICAM1 (intercellular adhesion molecule 1)
Diseases named in the same sentence as ICAM1 in open-access papers (continued):
Sharing a sentence is not in itself a finding about the gene and the disease.
acute pancreatitis (12 papers, 2009 to 2025). An acute inflammatory process that leads to necrosis of the pancreatic parenchyma. "A vital role of ICAM-1 in the action of neutrophils in acute pancreatitis was shown in a study in which genetically deficient mice in ICAM-1 were protected against acute pancreatitis and associated lung injury." (PMID 34830018, 2021). "However, it has been reported that the devastating effects of acute pancreatitis and associated lung injury occur less frequently in ICAM-1 knockout mice." (PMID 40005317, 2025). "High serum levels of ICAM-1 have been detected in acute pancreatitis, especially in severe and/or necrotizing acute pancreatitis." (PMID 34830018, 2021). "It has been shown that increased expression of Icam1 protects lung against injury by neutralizing antibodies or targeted gene deletion during bacterial sepsis, acute pancreatitis and trauma." (PMID 20628605, 2010). "As ICAM1 could promote the recruitment and infiltration of leukocytes, blockade of ICAM1 using monoclonal antibodies exerted anti-inflammatory effect in acute pancreatitis, thus attenuating both local pancreatic injury and systemic lung injury." (PMID 34408980, 2021). "Adhesion molecules like ICAM-1 and PECAM-1 are scarcely expressed in endothelial cells, but increase in acute pancreatitis." (PMID 25265022, 2014). "ICAM-1, VCAM-1, E-selectin and P-selectin have been found to play an important pro-inflammatory role in various models of acute pancreatitis." (PMID 20040116, 2009).
acute respiratory distress syndrome (12 papers, 2013 to 2025). Progressive and life-threatening pulmonary distress in the absence of an underlying pulmonary condition, usually following major trauma or surgery. "Intercellular cell adhesion molecule 1 (ICAM1) has been confirmed to be abnormally expressed in acute respiratory distress syndrome (ARDS) patients." (PMID 40329406, 2025). "The acute lung injury and acute respiratory distress syndrome spectrum of diseases represents another promising area for ICAM-1 targeting, particularly for directing other therapeutic agents to the pulmonary area." (PMID 37237555, 2023). "MALAT1 targeted miR-150-5p to exacerbate acute respiratory distress syndrome by upregulating ICAM-1 expression." (PMID 34012919, 2021). "An increased number of ICAM-1+ neutrophils were shown to accumulate in the lung tissue during sepsis, leading to acute respiratory distress syndrome (ARDS)." (PMID 30944838, 2019). "USP7‐mediated ICAM1 induced apoptosis, inflammation, oxidative stress, and M1 macrophage polarization, while suppressed proliferation in LPS‐induced HPMECs via activating NF‐κB pathway, thus accelerating the progression of pediatric acute respiratory distress syndrome." (PMID 40329406, 2025). "ICAM-1 activates leukocytes and endothelial cells (ECs), which in turn prompt the release of various inflammatory mediators, resulting in systemic inflammatory response syndrome (SIRS), acute respiratory distress syndrome (ARDS) and multi-organ dysfunction syndrome (MODS)." (PMID 24116078, 2013).
anaemia (12 papers, 2009 to 2023). "The increased circulatory VCAM-1 and ICAM-1 levels in CA mice further underline these findings implicating the role of anemia in inflammation and associated changes in the endothelium." (PMID 37234375, 2023). "It is likely that local production of cytokines in the tissues in response to sequestering parasites would further enhance the expression of ICAM-1 in the wild-type host, contributing both to weight loss and the development of anaemia." (PMID 28468674, 2017). "Cytoadhesion molecules such as ICAM1 contribute to cytoadhesive phenotype/rosetting and high intensity of rosetting is found in anaemia cases with P. vivax infection." (PMID 25889165, 2015). "This was true even when plasma soluble ICAM-1 levels were corrected for the degree of anaemia in each patient." (PMID 20712868, 2010). "In our cohort, soluble EC activation biomarkers (e.g. ICAM-1, VCAM-1, E-selectin, Ang-2, CD40L, vWF-A2) and the EC damage product, Syndecan-1, are positively correlated with thrombocytopenia, lymphopenia, anaemia, and neutrophil enrichment in the peripheral blood." (PMID 34585667, 2021). "This is suggestive of a mechanistic hypothesis in which malaria coma is potentially driven by both ICAM-1 and EPCR binding parasites, in contrast with anemia." (PMID 31040236, 2019). "Strikingly, we also observed increased plasma ICAM-1 and VCAM-1 levels in chronic coronary syndrome (CCS) patients with anemia compared to non-anemic patients." (PMID 37234375, 2023).
cerebral infarction (12 papers, 2011 to 2025). An ischemic condition of the brain, producing a persistent focal neurological deficit in the area of distribution of the cerebral arteries. "ICAM1, as a potential molecular target, holds promise for optimizing stent implantation outcomes and reducing the incidence of complications such as cerebral infarction." (PMID 41404041, 2025). "Our results support those reported in the Framingham cohort study, where ICAM‐1 levels were associated with higher WMH volume and silent brain infarcts." (PMID 40275856, 2025). "Alternatively, circulating immune cells can be activated, with blood–brain barrier damage after cerebral infarction, promoting the expression of cell adhesion molecules (ICAM-1, VCAM-1) in vascular endothelial cells." (PMID 37111353, 2023). "Cerebral levels of IL-6, IL-10, TNF-α, NF-κB p65, and ICAM-1, besides cerebral infarct volume, were significantly elevated in control and vehicle related to sham groups, while total antioxidant capacity was markedly reduced." (PMID 36567842, 2022). "Ferulic acid (eg 80 and 100 mg/kg, i.v.)reduces the size of cerebral infarction and neurological deficit scores and inhibits ICAM-1 and NF-κB expression in transient MCAo rats." (PMID 21867503, 2011). "In addition, increased expression of other inflammatory markers, such as intercellular adhesion molecule 1, and decreased levels of myeloperoxidase, were associated with more severe WMH and the occurrence of cerebral infarctions in CSVD patients." (PMID 41000387, 2025). "Therefore, anti-inflammation, such as inhibition of pro-inflammatory cytokine and ICAM-1, is very important in treating cerebral infarction." (PMID 21867503, 2011). "Histopathological analysis and measurement of brain infarct size were performed, and cerebral levels of IL-6, IL-10, TNF-α, ICAM-1, NF-κB p65, and total antioxidant capacity were assessed." (PMID 38313176, 2023). "In addition to brain infarct volume and histopathological assessment, the brain tissues were harvested to evaluate cerebral IL-6, IL-10, TNF-α, ICAM-1, NF-κB p65, and total antioxidant capacity levels." (PMID 36567842, 2022).
cognitive decline (12 papers, 2016 to 2025). "ICAM-1 is associated with progression of depressive symptoms, cognitive decline and cardiovascular disease." (PMID 27827896, 2016). "We investigated the relationship between baseline circulating levels of inflammatory (TNF-α, IL-1ß) and endothelial cell markers (VCAM-1, ICAM-1, E-selectin) and 18-month cognitive decline (ADAS-cog12) in 266 mild-to-moderate AD patients from the NILVAD study." (PMID 39085534, 2025). "The most important pro-inflammatory mediators associated with motor and cognitive decline as well as with neurodegenerative/PD-specific biomarkers were FABP, ICAM-1, IL-8, MCP-1, MIP-1-beta, and SCF." (PMID 35280273, 2022). "Increased ICAM-1 detection in the hippocampus likely indicates mechanisms of ongoing inflammation in this brain region and may contribute to cognitive decline that occurs in TBI55." (PMID 28630485, 2017). "Inflammatory cytokines, including IL-6, IL-10, CRP, MCP-1, ICAM-1, and TNF-α, play an important role in the development of poststroke cognitive decline." (PMID 35111122, 2021). "Likewise, CSF markers of endothelial injury, including ICAM‐1 and VCAM‐1, were elevated in preclinical AD in relation to CSF tau, cortical thinning, and cognitive decline." (PMID 41319164, 2025). "Our study's findings contribute to the existing literature by suggesting that inflammatory markers (TNF-α and IL-1ß) and endothelial cell markers (E-selectin, ICAM-1, and VCAM-1) have neither cross-sectional nor longitudinal associations with cognitive decline in AD patients." (PMID 39085534, 2025).
fibrosis (12 papers, 2014 to 2023). the formation of excess fibrous connective tissue in an organ or tissue in a reparative or reactive process. "The protein expression of FN and ICAM-1, both markers of inflammatory fibrosis in kidney tissues, was increased in db/db mice, which reversed by Fr treatment." (PMID 35401165, 2022). "In bleomycin-induced fibrosis, a commonly used mouse model of SSc, deficiency of CD62L and/or ICAM-1 has been shown to suppress fibrosis in the skin and lungs and to reduce the number of macrophages in affected tissues among other leukocyte perturbances." (PMID 35216350, 2022). "Previous studies have revealed that proposed biomarkers, VCAM-1, ICAM-1, and CD62P with higher concentrations are independently associated with fibrosis." (PMID 31922200, 2020). "We analyzed the inflammation by observing the monocyte chemotactic factor-1 (MCP-1) and intercellular adhesion molecule (ICAM-1) expression and calculated the tubulointerstitial fibrosis area by Masson staining." (PMID 28626343, 2017). "A recent study has shown that L-selectin and ICAM-1 regulate Th2 and Th17 cell accumulation in the skin and lungs, leading to the development of fibrosis in a bleomycin-induced fibrosis model." (PMID 24516598, 2014). "Similarly, for cardiac phenotypes, we identified multiple genes related to cardiac fibrosis that were up-regulated in FRDAkd mice heart, including Lgals3, Icam1 and Timp1." (PMID 29257745, 2017). "In PCV, patients with fibrosis but not those without, had significantly higher levels of ICAM-1 and VCAM-1 compared to controls." (PMID 37985993, 2023).
metastatic tumors (12 papers, 1997 to 2023). "In pigmented metastatic tumors, high expression of ITGAV in specimens possessing low ICAM-1 was associated with dismal survival (median post-surgery survival 1.4 months, HR = 20.0, p = 0.014)." (PMID 30116025, 2018). "Our findings confirmed that CD45+F4/80+ macrophages were more highly abundant in metastatic tumors in ICAM-1−/− mice than in WT mice." (PMID 26068788, 2015). "We found that the expression of M2-specific cytokines such as interleukin (IL)-13, IL-10, and transforming growth factor-β (TGF-β) was markedly increased in hepatic metastatic tumors of ICAM-1−/− mice compared with that in WT mice." (PMID 26068788, 2015). "Our findings demonstrate a novel role for ICAM-1 in suppressing M2 macrophage polarization via downregulation of efferocytosis in the tumor microenvironment, thereby inhibiting metastatic tumor progression." (PMID 26068788, 2015). "Increased serum concentrations of VCAM-1 were associated with locally advanced and metastatic disease whereas ICAM-1 was significantly elevated both in local and in advanced/metastatic disease." (PMID 9400933, 1997). "All recipient mice remained clinically well after an average of 100 d, but contained numerous ZSG+/Cdh1+/Icam1+ donor-cell clusters within their lungs, liver, kidneys and peritoneum at a frequency similar to metastatic tumors formed by tail-vein injections of tCZCs." (PMID 36175792, 2022). "Therefore, the stability of ICAM-1 is increased in metastatic tumors via the ERK pathway-mediated downregulation of FBXO4." (PMID 29137327, 2017). "Moreover, TUNEL analysis revealed a significant decrease in the presence of apoptotic nuclei in hepatic metastatic tumors of ICAM-1−/− mice compared with their WT counterparts." (PMID 26068788, 2015). "Quantitative RT-PCR further confirmed that ICAM-1 deficiency significantly upregulated mRNA levels of IL-10, TGF-β, chemokine (C–C motif) ligand 17 (CCL17), CCL22 (M2-specific cytokines or chemokines) in hepatic metastatic tumors." (PMID 26068788, 2015). "Levels of circulating ICAM-1 and VCAM-1 were increased both in patients with local and those with metastatic disease." (PMID 9667659, 1998). "Our results are not exactly consistent with a previous report, in which ICAM-1 was found to suppress M2 macrophage polarization and inhibit metastatic tumor progression." (PMID 29340098, 2017). "Tumors at all stages showed negative staining for E-cadherin, whereas metastatic tumor at all generations showed negative staining for E-cadherin, ICAM-1, VCAM-1, and CK8/18." (PMID 26847082, 2016). "A preliminary treatment study in the 4T1 model with a low dose indicated that ICAM-1-targeted GT DcNP-LFA1-P may provide additional metastatic tumor nodule reduction beyond that of non-targeted GT DcNPs and GT-free drugs." (PMID 35056985, 2021). "These metastatic tumors revealed no detectable expression of CK8/18, E-cadherin, VCAM-1, and ICAM-1." (PMID 26847082, 2016). "Immunofluorescence staining showed that ICAM-1 was abundantly expressed in macrophages in hepatic metastatic tumors of WT mice, with no ICAM-1 expression in ICAM-1−/− mice." (PMID 26068788, 2015). "Interestingly, E-cadherin, ICAM-1, VCAM-1 and CK8/18 are not expressed in the implanted and metastatic tumor tissues of nude mice, suggesting that the molecular and biological characteristics of the implanted and metastatic tumors are different from the original tissue obtained surgically." (PMID 26847082, 2016).
Anxiety (11 papers, 2016 to 2024). Intense feelings of nervousness, tension, or panic often arise in response to interpersonal stresses. "ICAM-1 upregulation in the vasculature of brain regions has been previously implicated in fear and anxiety responses." (PMID 34135004, 2021). "In rodents, social defeat and consequent anxiety-like behaviour is associated with the recruitment of myeloid cells to the brain, facilitated by increased expression of intracellular adhesion molecule 1 (ICAM-1) on neurovascular endothelial cells." (PMID 33723234, 2021). "On the contrary, anxiety-like behavior was similar in Control IgG and anti-ICAM1 mice." (PMID 32687056, 2020). "Similar results were reported in mice under acute stress conditions, where the migration of T-cells into the choroid plexus (located in the brain ventricles) resulted in an induction of glucocorticoids to the expression of the intercellular adhesion molecule 1 (ICAM1), with reduced anxiety." (PMID 32517269, 2020). "No psychological factors were associated with serum ICAM-1 levels (for anxiety: β=5.11, p=0.51; other psychological factors exhibited similar associations)." (PMID 26733571, 2016). "The graphic representation between anxiety levels of our sample of SLE patients and analyzed biomarkers suggest that ANA, Anti B2 GP1, ICAM 1, Anti RIB P and LA values increase as the anxiety level becomes severe or very severe." (PMID 36979502, 2023).
chronic kidney disease (11 papers, 2010 to 2026). Impairment of the renal function secondary to chronic kidney damage persisting for three or more months. "Chronic kidney disease (CKD) is associated with increased procoagulants, including cystatin C, C-reactive protein, interleukin-6, tumor necrosis factor-α soluble receptor 1, intercellular adhesion molecule-1, fibrinogen, and factor VIII." (PMID 30115029, 2018). "Our study showed that the expression level of VCAM-1 and ICAM-1 increased in rats with chronic renal failure, which was inhibited by SKI treatment." (PMID 35674582, 2022). "Both human and mouse atherosclerotic tissue, as well as arteriovenous fistulas (AVF) of advanced chronic kidney disease patients, were evaluated for the presence of ICAM-1 N-glycoforms." (PMID 32208424, 2020). "In a cohort of 142 HD patients, we examined the potential of serum ICAM-1 as a CVD biomarker and evaluated whether confounding factors, including low-grade inflammation and chronic kidney disease-mineral bone disorder (CKD-MBD), limit its diagnostic value." (PMID 41594641, 2026). "Chronic kidney disease (CKD) is associated with low-grade inflammation that activates nuclear factor–κB (NF–κB), which upregulates the expression of numerous NF–κB responsive genes, including the genes encoding IL-6, ICAM-1, VCAM-1, and MCP-1." (PMID 36012158, 2022). "Several studies have reported that urinary ICAM1 is increased in acute renal allograft rejection, chronic kidney disease (CKD) and lupus nephritis." (PMID 30547763, 2018).
Hepatitis (11 papers, 2013 to 2023). Inflammation of the liver. "It appears that an increase in IL-6, TNF-α, and s-ICAM-1 in the course of EBV infection may indicate the risk of hepatitis with concomitant biliary pole damage." (PMID 37834802, 2023). "Increased concentrations of IL-6, TNF-α, and s-ICAM-1 may indicate the risk of hepatitis with concomitant biliary pole damage during EBV infection." (PMID 37834802, 2023). "However in the hepatitis group the scatter plot of ICAM-1 vs BHI suggests that the association might be present." (PMID 33520470, 2021). "It was shown that IL-6, TNF-α, and s-ICAM-1 concentrations were the highest in patients with hepatitis and biliary pole damage." (PMID 37834802, 2023). "While the ICAM-1 and sVCAM-1 significantly increased in the hepatitis group, VEGF-A significantly decreased." (PMID 33520470, 2021). "While the ICAM-1 and sVCAM-1 were significantly increased in the hepatitis group, VEGF-A was significantly decreased." (PMID 33520470, 2021). "Studies with ICAM-1 knockout mice revealed that ICAM-1 plays a role in the development of ConA-induced hepatitis by regulating leukocyte infiltration and subsequent cytokine production." (PMID 33809904, 2021). "In this article, siRN As targeted at the mRN A of theintracellular adhesion protein ICAM-1 gene, whose expressionis elevated in liver endothelial cells in the early stages of hepatitis, wereused." (PMID 24303201, 2013). "Therefore, hepatitis accompanied by cholestasis increases de novo ICAM-1 expression within sinusoidal endothelial cells and Kupffer cell." (PMID 37834802, 2023). "However, in the hepatitis group, BHI was moderately associated with ICAM-1 at the 0.1 significance level indicating the need for further studies with a larger number of participants including post-DAA HCV patients." (PMID 33520470, 2021). "Hepatocyte-derived lipotoxic EVs contain DAMPs and cell adhesion molecules such as S100a11 and ICAM1, which might affect immune cell responses, thus promoting liver inflammation in NASH." (PMID 34805145, 2021). "The results suggested that CyA might inhibit Con A-induced liver inflammation by lowering elevated levels of IL-1β and ICAM-1." (PMID 30893870, 2019). "Furthermore, ICAM-1 has been reported to contribute to the development of hepatitis by mediating adhesion and supporting the migration of lymphocytes into the liver." (PMID 28377718, 2017). "The pro-inflammatory markers IL-1α, IL-1β, IL-6, TNF, ICAM-1, and VCAM-1 were all significantly upregulated under both hepatitis models." (PMID 29445190, 2018). "In ConA-induced hepatitis, the expression of chemokines and adhesion molecules were demonstrated to play important roles in recruiting lymphocytes into the liver to aggravate liver injury, such as MIP-1α, CXCL10, and ICAM-1." (PMID 28377718, 2017).